C9 (complement C9)
Diseases named in the same sentence as C9 in open-access papers (continued):
Sharing a sentence is not in itself a finding about the gene and the disease.
Achalasia (1 paper, 2023). A disorder of esophageal motility characterized by the inability of the lower esophageal sphincter to relax during swallowing and by inadequate or lacking peristalsis in the lower half of the body of the esophagus. "In the current study, complement C1q, C1s, C2, C3, C4-A, C4-B, C5, C6, and C9 were all upregulated in the achalasia group." (PMID 37324545, 2023).
aortic valve stenosis (1 paper, 2019). Aortic valve stenosis (AVS) is a condition characterized by narrowing of the heart's aortic valve opening. "We detected an upregulation of complement 9 (C9), serum amyloid P-component (APCS) and transgelin as well as downregulation of heat shock protein (HSP90), protein disulfide isomerase A3 (PDIA3), annexin A2 (ANXA2) and galectin-1 in patients with aortic valve stenosis." (PMID 31856737, 2019).
Atrophy (1 paper, 2016). Any weakening or degeneration, especially through lack of use. "Among the C9 + phenotypes, atrophy was most severe in C9 + patients with clinical features of bvFTD." (PMID 27995069, 2016). "Because we did not detect significant atrophy in the asymptomatic C9 + subjects in this study, it is less likely to reflect a developmentally acquired condition." (PMID 27995069, 2016).
Behcet disease (1 paper, 2022). A chronic, relapsing, multisystemic vasculitis characterized by mucocutaneous lesions, as well as articular, vascular, ocular and central nervous system manifestations. "HPT and C9 are reported to be closely associated with Behcet’s disease (BD)." (PMID 35274006, 2022).
Brain atrophy (1 paper, 2018). Partial or complete wasting (loss) of brain tissue that was once present. "The diffuse nature of the brain atrophy, involving cortical and subcortical structures, has led to the suggestion that changes in ventricular volume be used to follow longitudinal disease progression in C9+ carriers." (PMID 30568632, 2018). "Notably, C9+ ALS patients had significantly higher pNFH levels than C9– ALS patients, which presumably reflected increased neurodegeneration, consistent with reports that patients with C9+ ALS develop greater brain atrophy, particularly in extra-motor regions, compared to C9– ALS patients." (PMID 30568632, 2018).
brain tumors (1 paper, 2023). "For example, similar expression levels of NDRG1, LDHA, MHCII molecules, interferon genes, GPM6A, C9, and SRGAP2 were discovered in different myeloid subpopulations, indicating the similar functional states in different brain tumors." (PMID 38094301, 2023).
breast tumor (1 paper, 2019). "Treatment with the SMR peptide antagonists reduced the concentration of mortalin and C9 in EVs released from the two breast tumor lines and the lymphocytic tumor line." (PMID 31534628, 2019).
chondrocalcinosis (1 paper, 2023). An acute episode of pain, swelling, and redness, sometimes associated with fever. "To exclude cross-reactions between C9 immunostaining and other inflammatory joint conditions, we included tissue samples of a separate cohort with rheumatoid arthritis, wear particles and chondrocalcinosis." (PMID 36895567, 2023).
chronic hepatitis B (1 paper, 2022). "C9 level was also marked low in sera/liver of chronic hepatitis B (CHB) and Immune-tolerant (IT) patients than inactive carriers and healthy controls." (PMID 36376872, 2022).
chronic kidney disease (1 paper, 2025). Impairment of the renal function secondary to chronic kidney damage persisting for three or more months. "Importantly, intrarenal complement gene expression (C1R, C1QB, C6, C9, C5, MASP2) predicts nonresponse to induction therapy, alluding to the potential pathogenic role of intrarenal complement gene expression in chronic kidney disease." (PMID 41031884, 2025).
coagulopathy (1 paper, 2025). "Remarkably, main hub proteins in the CR group were VTN, C3, C4B, C9, and CFH that play a major role in the complementary pathway, which has gained increased attention as a major contributor to cancer‐related coagulopathy." (PMID 40079446, 2025).
Crohn disease (1 paper, 2024). A gastrointestinal disorder characterized by chronic inflammation involving all layers of the intestinal wall, noncaseating granulomas affecting the intestinal wall and regional lymph nodes, and transmural fibrosis. "Other notable markers up-regulated selectively in CD submucosa/wall compared to control include IL36a, IL16, and complement C9, while C6 is selectively increased in mucosa, highlighting a potential and perhaps underappreciated role for complement in the pathogenesis of Crohn’s disease." (PMID 38791146, 2024).
dengue (1 paper, 2020). "Our data also indicate that the levels of C2, C4b, C5, C5a, C9, factor D and factor I are significantly associated with clinical parameters, especially with platelet counts, of dengue patients." (PMID 32913345, 2020). "The levels of the complement proteins C2, C4b, C5, C5a, C9, factor D and factor I are modulated in dengue patients during the clinical course of dengue." (PMID 32913345, 2020). "We measured the levels of MBL and the complement proteins C2, C4b, C5, C5a, C9, adipsin (factor D) and factor I in serum samples of dengue and DWS patients and healthy controls." (PMID 32913345, 2020).
dermatitis (1 paper, 2024). An inflammatory process affecting the skin. "The membrane attack complex (MAC) and their components (complement proteins C6, C7, C8 and C9) have been increased in PRGF supernatant from patients with dermatitis." (PMID 39062477, 2024).
endothelial dysfunction (1 paper, 2025). In vascular diseases, endothelial dysfunction is a systemic pathological state of the endothelium (the inner lining of blood vessels) and can be broadly defined as an imbalance between vasodilating and vasoconstricting substances produced by (or acting on) the endothelium. "Upregulated proteins (e.g., CRP, C9, APOC1) correlated with visceral adiposity, systemic inflammation, and endothelial dysfunction." (PMID 40981199, 2025).
epilepsy (1 paper, 2024). A brain disorder characterized by episodes of abnormally increased neuronal discharge resulting in transient episodes of sensory or motor neurological dysfunction, or psychic dysfunction. "Our study found increased C9 expression in the epilepsy group." (PMID 39063177, 2024).
esophageal cancer (1 paper, 2023). A primary or metastatic malignant neoplasm involving the esophagus. "C9 is the terminal Component of the complement cascade, which has also been found to be elevated in serum of gastric, lung, colorectal and esophageal cancers through proteomics or glycoproteomic approaches." (PMID 37147936, 2023).
fragile X syndrome (1 paper, 2022). A genetic syndrome caused by mutations in the FMR1 gene which is responsible for the expression of the fragile X mental retardation 1 protein. "We found that co-transduction of C9-ALS/FTD iMNs resulted in a shift from amplification of a 523 bp product to the 320 bp product in cells treated with AAV9–SpCas9 and either gRNA pair, but not in C9-ALS/FTD or fragile X syndrome control iMNs without transduction with AAV9–SpCas9." (PMID 36271076, 2022).
gastro-esophageal reflux (1 paper, 2022). "As C9 transcript was reported to be increased in a rat model of gastro-esophageal reflux, we considered the possibility that reflux induces epithelial expression of C9." (PMID 35345676, 2022).
glomerular diseases (1 paper, 2014). "Several previous studies using immune electron microscopy found deposition of complement components and/or complement C5b-C9 complexes in extracellular organized structures, which are morphologically similar to microspheres, in the GBM in various kinds of glomerular diseases." (PMID 24528497, 2014).
heart failure (1 paper, 2025). Inability of the heart to pump blood at an adequate rate to meet tissue metabolic requirements. "Cox regression models adjusted for covariates in a cohort of 185 heart failure patients identified complement and coagulation-related proteins (C3, C7, C8, C9, F9) as significant predictors of disease progression." (PMID 41158877, 2025).
Hepatic steatosis (1 paper, 2025). Steatosis is a term used to denote lipid accumulation within hepatocytes. "The top predictive proteins for hepatic steatosis included TNC, GAPDH, CA2, and C9, underscoring the role of inflammatory mediators and lipid-handling proteins in this condition." (PMID 40981199, 2025).
hippocampal atrophy (1 paper, 2024). "Additionally, the C9+ ALS‐FTD was associated with more extensive hippocampal atrophy, suggesting a genotype–phenotype relationship." (PMID 38334254, 2024).
ischemic stroke (1 paper, 2024). A stroke disorder caused by obstruction of blood flow to the brain, due to thrombotic (local blood clot formation) or embolic (due to a blood clot or other material traveling from another site) event. "More recent work has demonstrated that the activation of CMKLR1 by C9 peptide mitigates NLRP3 inflammasome-mediated neuronal pyroptosis in ischemic stroke, suggesting that C9 may have a more complicated regulatory role in inflammation." (PMID 39595036, 2024).
lupus nephritis (1 paper, 2024). Glomerulonephritis in the context of systemic lupus erythematosus. "This study highlights the importance of looking at the balance between complement activation (e.g., MAC complex) and regulation (e.g. CD 59) in evaluating complement biomarkers and suggests C3, CFI and C9-to-CD59 ratio may be a marker of tubulointerstitial disease in lupus nephritis." (PMID 38895123, 2024). "We found that lupus nephritis patients with moderate to severe IFTA have increased urinary C3, CFI, and C9-to-CD59 ratio as compared to those with none to mild IFTA." (PMID 38895123, 2024).
malnutrition (1 paper, 2014). Inadequate nutrition resulting from poor diet, malabsorption, or abnormal nutrient distribution. "Few studies assessed C6, C9, and factor B, and most found reduced levels in malnourished children, most so in oedematous malnutrition." (PMID 25153531, 2014).
Mitral stenosis (1 paper, 2018). An abnormal narrowing of the orifice of the mitral valve. "C9, the last MAC complement, was indeed exclusively found in RHD patients with mitral stenosis, compared to control subjects." (PMID 30619357, 2018).
motor neuron degeneration (1 paper, 2026). "Furthermore, in mouse models, C9‐KO or C9‐HRE and the presence of RNA foci and DPRs have been shown to be insufficient to cause motor neuron degeneration, although loss of C9ORF72 can lead to synaptic dysfunction and excitotoxicity." (PMID 40952044, 2026).
motor neuron disease (1 paper, 2020). "Finally, a recent RNA-Seq study comparing C9 FTLD and FTLD/motor neuron disease patients with unaffected control individuals reported a highly significant decrease in C9orf72 RNA levels in C9 FTLD samples; however, this data showed no significant change in SMCR8 or WDR41 RNA expression." (PMID 32678027, 2020).
myotonic dystrophy (1 paper, 2017). An inherited progressive disorder affecting the muscles. "The discovery of DPRs has fueled research not only on C9 but also the repeat-related diseases such as Fragile X-associated tremor ataxia syndrome (FXTAS) and myotonic dystrophy (DM1), which opens up a new aspect of the pathology of neurodegenerative disease." (PMID 28973350, 2017).
nasopharyngeal carcinoma (1 paper, 2014). A carcinoma arising from the nasopharyngeal epithelium. "A significant association of CR2 SNP (rs3813946) with the development of nasopharyngeal carcinoma was indicated in Cantonese population, and the genetic variations of complement system genes C5 and C9 plays a potential role in susceptibility to non-Hodgkin lymphoma (NHL)." (PMID 24621201, 2014).
nephritis (1 paper, 2023). Inflammation of renal tissue. "Using mass spectrometry, we found an increase in the level of complement components C3, C4b, C5, C9, and CFB in the urine of patients with active nephritis." (PMID 37108355, 2023).
ovarian carcinoma (1 paper, 2021). A malignant neoplasm originating from the surface ovarian epithelium. "CSMD1 has been shown to inhibit the deposition of complement factors C3b and C9 on ovarian cancer cells and promote the degradation of C3b, thereby potentially inhibiting an antitumour immune response." (PMID 33506581, 2021).
proliferative diabetic retinopathy (1 paper, 2011). Advanced retinopathy due to diabetes mellitus characterized by the formation of new vessels in the retina. "Activation of the complement pathway has been demonstrated by increased protein expression of several factors such as C3, C4b, C9 and factor B in the vitreous of diabetic patients with proliferative diabetic retinopathy." (PMID 22046295, 2011).
reactive arthritis (1 paper, 2022). Reactive arthritis (ReA) is an autoimmune disorder belonging to the group of seronegative spondyloarthropathies and is characterized by the classic triad of arthritis, urethritis and conjunctivitis. "C9 may be responsible for the cartilage degradation leading to joint tissue damage in the autoimmune and reactive arthritis conditions." (PMID 35433699, 2022).
retinal degeneration (1 paper, 2023). Degeneration of the retina. "The results showed that proteins like CST3, C9, and ITM2B, among others, are associated with retinal degeneration while proteins such as COL1A2, IGFBP2, and AGT, among others, are associated with diabetic complications." (PMID 37884923, 2023).
Rickettsia infection (1 paper, 2018). "Analysis of infection in these mice indicated that C9 is completely dispensable for immunity and that the MAC plays no role in controlling Rickettsia infection." (PMID 29581196, 2018).
Senile plaques (1 paper, 2006). Senile plaques are extracellular deposits of amyloid in the gray matter of the brain. "Goat anti-C9 was used rather than monoclonal anti-C5b-9 for assessment of late-stage complement activation because, in preliminary studies, more consistent staining of senile plaques in AD hippocampus sections was obtained with the anti-C9 antibody." (PMID 17052351, 2006).
spinocerebellar ataxia 2 (1 paper, 2016). "For example, ATXN2 encodes a polyglutamine protein associated with spinocerebellar ataxia 2 and contains an expansion that also confers increased susceptibility to ALS in sporadic, and possibly C9, cases." (PMID 27623008, 2016).
steatosis (1 paper, 2021). Increased lipid within the cytoplasm of cells. "A Wilcoxon test on C9 and C4BPA genes revealed gene downregulation within the steatosis samples." (PMID 34829865, 2021).
strongyloidiasis (1 paper, 2014). An infection that is caused by nematodes of the genus Strongyloides, most commonly Strongyloides stercoralis, which is a soil-transmitted helminth, and which is characterized by a variety of gastrointestinal, dermatologic, and, occasionally, pulmonary manifestations. "Thus, the low cross-reactivity observed for the C9 clone, with satisfactory specificity (80%), suggest its use as a promising antigen in the serodiagnosis of strongyloidiasis, which may also include the C10 clone (77.5%)." (PMID 24874206, 2014).
temporal lobe epilepsy (1 paper, 2024). A localization-related (focal) form of epilepsy characterized by recurrent seizures that arise from foci within the temporal lobe, most commonly from its mesial aspect. "Several apolipoproteins (APOA1, APOD, and APOA4), serpin protease inhibitors (SERPINA3, SERPINF1, etc.), complement components (C9, C8, and C1R), and a total of 42 proteins were found to be significantly upregulated in the temporal lobe epilepsy group." (PMID 39063177, 2024).
thrombophilia (1 paper, 2018). A condition characterized by an abnormally high level of thrombi. "As a result, anti-C9 antibody was detected in 2 of 13 specimens from SN-APS patients without known thrombophilia (no.15, No.16), and in 1 of 13 specimens of SN-APS patients with thrombophilia (No. 4); no band was detected in the four control samples." (PMID 29894483, 2018).
vitamin D deficiency (1 paper, 2023). A nutritional condition produced by a deficiency of VITAMIN D in the diet, insufficient production of vitamin D in the skin, inadequate absorption of vitamin D from the diet, or abnormal conversion of vitamin D to its bioactive metabolites. "Moreover, vitamin D deficiency resulted in the abnormal expression of 56 differential proteins, among which the expression levels of complement factor B, complement component C9, inducible co-stimulator ligand, and peptidase inhibitor 16 significantly changed with the decrease in vitamin D content." (PMID 36178657, 2023). "The results showed that vitamin D deficiency led to the abnormal expression of CFB, TPM4, C9, ICOSL, and PI16." (PMID 36178657, 2023).